BRCA1 (BRCA1 DNA repair associated)
Diseases named in the same sentence as BRCA1 in open-access papers (continued):
Sharing a sentence is not in itself a finding about the gene and the disease.
breast cancer (continued). "Moreover, this PML risk panel test was positive for 10.9% of PML cases in our study, which is higher than the presence of BRCA1 and BRCA2 variants in breast cancer patients (2.8 and 2.7%, respectively)." (PMID 36588876, 2022). "Indeed, BRCA1 and BRCA2 mutation carriers have risks of 57% and 49%, respectively, for developing breast cancer." (PMID 36140723, 2022). "The lack of genetic testing results of BRCA1/2 mutations for these very young female breast cancer patients and the lack of family support and economic situation were other limitations." (PMID 35280812, 2022). "One example was PRS for breast cancer, where enhanced screens (mammograms) were likely, but not proven, to benefit women with highest risk scores, by analogy with BRCA1&2." (PMID 35488921, 2022). "The BRCA1 and BRCA2 genes, are best known as breast cancer susceptibility genes." (PMID 35413944, 2022). "Comparatively, other Hox family members like HOXA9 may exhibit tumor suppressive roles by upregulating the expression of BRCA1 in breast cancer cells." (PMID 35846378, 2022). "Mutations in BRCA1/2 genes were detected in approximately 12%–25% of patients with high‐grade serous ovarian carcinoma (HGSC) while the prevalence of BRCA1/2 mutation was (3.7%–4.7%) in women with breast cancer, aged between 40 and 59 years." (PMID 35608067, 2022). "However, studies have shown that the combination of BRCA1 and BRCA2 mutations accounts for the most high-risk breast cancer families." (PMID 35740092, 2022). "In this study, we built a new model (ARiCa: Asian Risk Calculator) for estimating the likelihood of carrying a pathogenic variant in BRCA1 or BRCA2 gene, using germline BRCA genetic testing results in a cross-sectional population-based study of 8,162 Asian breast cancer patients." (PMID 35143328, 2022). "Additionally, in the PrECOG 0105 phase 2 trial (NCT00813956), clinical responses of wild-type BRCA1/2 breast cancer to cisplatin patients were higher in patients classified as HRD defined as a LOH score ≥10." (PMID 36077694, 2022). "The authors found a significant reduction in ovarian cancer risk and no increase in breast cancer risk for both BRCA1 and BRCA2 carriers." (PMID 35884518, 2022). "Inherited mutated BRCA1 and BRCA2 genes also increase the risk of breast cancer." (PMID 35458452, 2022). "Next, we compared the distribution of high and low BRCAness score with DNA repair score and MKi67 expression with or without BRCA1-mutation in breast cancer." (PMID 36371386, 2022). "Most older patients with the BRCA1 and BRCA2 pathogenic variants in exons 12-24/25 with luminal breast cancer may gain a similar survival benefit from other risk-reducing strategies or surveillance." (PMID 36580360, 2022). "This “LOH reversal” was observed in two BRCA2 mutation carriers with breast cancer, treated with non-platinum chemotherapy and radiation, and two BRCA1 mutation carriers with ovarian cancer, both treated with platinums." (PMID 36344544, 2022). "Some studies showed that the overexpression of UBE2T could promote the proliferation of breast cancer cells by repressing BRCA1 expression." (PMID 36168930, 2022).
breast cancer (continued). "Therefore, clones of the breast cancer cell line MCF7 with indels in BRCA1 exon 9 and 14 were generated using CRISPR/Cas9." (PMID 36362151, 2022). "The AUC for the artificial neural network model was 0.903 (95% C.I. = 0.836–0.949, 0.858 for BRCA1 and 0.855 for BRCA2), while the AUC for nomogram predicting the risk of BRCA1/2 germline deleterious mutation in Chinese bilateral breast cancer patients was 0.828 (95% C.I. = 0.750–0.890)." (PMID 36324133, 2022). "As a corollary, maintaining physiological levels of glucose may improve BRCA1 function and delay breast cancer progression." (PMID 35432218, 2022). "Two primary risk factors of breast cancer development are mutations in the BRCA1 and BRCA2 genes, which can be linked to a family history of breast cancer, as well as the use of hormone-replacement therapy that causes extended exposure to female hormones, such as estrogen." (PMID 36012771, 2022). "In addition, 27% of carriers of the BRCA1 pathogenic variant and 19% of carriers of the BRCA2 pathogenic variant will develop a second primary contralateral breast cancer within 10 years after the first primary breast cancer diagnosis." (PMID 36580360, 2022). "However, several PTC-containing mRNAs generated by aberrant splicing evade the NMD pathway and are translated into truncated proteins in various diseases, such as β-globin in β-thalassemia and BRCA1 in breast cancer." (PMID 35456475, 2022). "Patients with heterozygous germline mutations of the BRCA1 or BRCA2 genes (for example, c.5266dupC, c.1961del, c.3700_3704del, c.3756_3759del, c.4035del in BRCA1, c.5946del in BRCA2, etc.)have an increased risk of developing breast cancer (BC), as well as ovarian and other cancers." (PMID 36613648, 2022). "First, females with a mutated BRCA1/2 gene are five times more likely to develop breast cancer than someone without a mutation." (PMID 35927682, 2022). "One of the most famous examples, mutations in BRCA1/BRCA2 genes, have given patients the ability to reliably assess their risk of developing breast cancer in their lifetime, as well as their risk of relapse after a first bout of breast cancer." (PMID 36010859, 2022). "At present, the risk estimates given to women by most healthcare professionals are broad (e.g., 35–85% lifetime risk of breast cancer for BRCA1 and BRCA2) and are not personalised." (PMID 35681696, 2022). "BRCA1 is reported to induce major energetic metabolism reprogramming in breast cancer cells." (PMID 36193432, 2022). "Common genetic variation in HMMR was proposed to be associated with breast cancer risk in carriers of pathological variants in BRCA1, but not in BRCA211,12." (PMID 35393420, 2022). "In our study, we assumed that RRBSO does not reduce the risk of contralateral breast cancer in carriers of the BRCA1 and BRCA2 pathogenic variants." (PMID 36580360, 2022). "Breast cancer occurs in many genetic factors, such as BRCA1/BRCA2 abnormalities." (PMID 36473847, 2022). "PALB2 mutation analysis in 94 breast cancer patients without BRCA1/2 mutations who had a family or personal history of PC showed a prevalence of 2.1%." (PMID 35761384, 2022). "Even though melatonin is known to downregulate the expression of BRCA1 genes that were elevated by estradiol stimulation in several breast cancer cell lines, not surprisingly, melatonin is associated with the nighttime elevation of BRCA1." (PMID 35897696, 2022). "These genes have a few similarities with the BRCA1/2 genes, but there is little evidence to suggest they also increase the risk of breast cancer as with BRCA1/2." (PMID 35805770, 2022). "Although the details remain unclear, the breast cancer suppressors BRCA1 and BRCA2 have been suggested to be involved in pathways that prevent R-loop accumulation." (PMID 36229463, 2022).
breast cancer (continued). "Our study is an advancement over previous ones due to the incorporation of variables from up-to-date peer-reviewed studies considering the type of pathogenic variant (BRCA1 or BRCA2), age at primary breast cancer diagnosis, breast cancer subtype and stage, status of systemic treatment received." (PMID 36580360, 2022). "Interestingly, all the patients with a germline BRCA1 or BRCA2 mutation and a second malignancy first developed a breast cancer and thereafter an OC." (PMID 36555431, 2022). "MLPA assay was employed to screen BRCA1 large genomic rearrangements in familial breast cancer patients with BRCA1 negative for small mutations." (PMID 34403063, 2022). "An awareness that breast cancer incidence is higher in younger patients (i.e., premenopausal patients) who carry a BRCA1/2mut may have also contributed to the high rate of BRCA1/2mut testing in Israel." (PMID 36358816, 2022). "Specifically, BRCA1/2 mutations in breast cancer result in dependency on the nonhomologous end-joining DNA repair pathway that is exploited by poly(ADP-ribose) polymerase inhibitors such as olaparib." (PMID 36040810, 2022). "Our evaluation of a racially/ethnically diverse cohort of women with unilateral breast cancer with pathogenic variants in BRCA1/2 showed no racial/ethnic difference in CPM use, but there was a higher post-CPM hazard of death among non-Whites than among Whites." (PMID 36685664, 2022). "Studies have revealed that BRCA1/2 carriers possess no change or an even further decrease in breast cancer risk while using short-term HRT to control symptoms following surgical menopause." (PMID 35685436, 2022). "Plasma sequencing using next-generation sequencing is an emerging companion diagnostic technology for various indications such as BRCA1/2 testing in ovarian cancer, ALK rearrangements in lung cancer and PIK3CA gene mutations in breast cancer patients eligible for treatment with alpelisib." (PMID 36428589, 2022). "A sample of 310 women carrying BRCA1/2 mutations (A) without a history of cancer or (B) with a history of unilateral breast cancer who have received post-test genetic counselling will be enrolled." (PMID 35172875, 2022). "Measures of clinical validity and utility compare favorably to other genetic risk tests, such as BRCA1 and BRCA2 screening for breast cancer risk and HLA-B*15:02 pharmacogenetic screening for pharmacovigilance of carbamazepine to prevent Stevens-Johnson Syndrome and Toxic Epidermal Necrolysis." (PMID 36588876, 2022). "Approximately 1–4% of all breast cancer cases are BRCA1-related." (PMID 36298462, 2022). "Breast cancer has similar BRCA1 and BRCA2 prevalence at 4.0 and 4.8%, respectively." (PMID 34979999, 2022). "Here, we report the largest WES study on germline DNA from Asian breast cancer patients who had undergone cancer risk assessment and were BRCA1 and BRCA2 mutation-negative." (PMID 36424660, 2022). "In this study, we identified recurrent somatic mutations and potential shared neoantigen candidates in BRCA1-positive, -negative, and germline BRCA1-mutated breast cancer." (PMID 36298462, 2022). "BRCA1/2 mutation prevalence varied widely from 1.8% in sporadic breast cancer to 36.9% in estrogen receptor/progesterone receptor low HER2 negative breast cancer." (PMID 35681784, 2022). "Breast cancer gene 1 (BRCA1) is a tumor suppressor gene that is key to breast cancer development." (PMID 36661673, 2022). "Breast cancer is also prevalent among women who have no family history of disorders, including inherited BRCA1/2 mutations." (PMID 35764927, 2022). "The sensitivity of HRDetect for predicting BRCA1/2 mutation in the validation cohort was 86% in ER+/HER2- breast cancer patients and showed sensitivity to detect PALB2 biallelic inactivation or RAD51C hypermethylation, and to reclassify BRCA1/2 VUS as germline PV." (PMID 35158866, 2022). "Approximately 20% of breast cancer tumors show an amplification of the BRCA1 gene." (PMID 36362151, 2022).
breast cancer (continued). "Predicted loss of function variants in BRCA1 and BRCA2 were present at increased frequencies in individuals with a breast cancer diagnosis and ovary as an additional cancer site, such that 28.6% and 13.6% of individuals, respectively, were a carrier for at least one variant in the burden set." (PMID 36199081, 2022). "Invasive breast cancers with BRCA1 mutations do not reveal more calcification on breast cancer-specific mammography." (PMID 35402620, 2022). "NCCN Guidelines for Breast Cancer V.1.2021 include NGS and comprehensive genomic profiling (CGP) as a method of detecting actionable mutations and fusions such as BRCA1/2 mutations, PIK3CA mutations, ESR1 mutation, HER2 mutation, MSI-H status, and deficient mismatch repair (dMMR)." (PMID 35804935, 2022). "The risk of contralateral breast cancer among carriers of germline pathogenic variants in BRCA1/2 with a primary diagnosis of breast cancer is 62–83% higher than in women not carrying these mutations over their lifetimes." (PMID 36685664, 2022). "A positive HRD score was validated to be associated with BRCA1/2 mutations and with response to platinum-based agents in the PrECOG 0105 breast cancer cohort (NCT00813956) even in the absence of BRCA1/2 mutations." (PMID 36077694, 2022). "Overall, 54.9% received BRCA1/2 testing within 6 months of breast cancer diagnosis." (PMID 35312162, 2022). "As there is virtually no genetic data on breast cancer (BC) in Colombians of African descent, we conducted a comprehensive BRCA1/2 mutational analysis of 60 Afro-Colombian families affected by breast/OC." (PMID 35641219, 2022). "Importantly, when compared with p18mt tumors, both p18mt;Gata3+/-and p18mt;Brca1+/-mammary tumors more frequently metastasized to the lungs, and the lung metastasis were also enriched with mesenchymal-like cells." (PMID 34373738, 2021). "For BRCA1 heterozygotes, the HRs for association between the ER-negative PRS313 and contralateral breast cancer risk were similar for heterozygotes of pathogenic variants, which lead to a stable mutant protein (class II) compared with those leading to no protein or an unstable protein (class I)." (PMID 34113011, 2021). "Specifically, retrospective analyses from the Breast Cancer Linkage Consortium showed a relative risk (RR) of PCa in male BRCA2 and BRCA1 mutation carriers of 4.65 (95% confidence interval (CI): 3.48–6.22) and 1.07 (95% CI 0.75–1.54) respectively, the latter being similar to the general population." (PMID 34830851, 2021). "There is evidence that combination therapies targeting tumors harboring BRCA mutations—such as PARP inhibitors—with PI3K pathway inhibition therapies may exhibit synergy in vivo for the treatment of endogenous BRCA1-related breast cancer mouse model." (PMID 34287479, 2021). "To test this hypothesis, we compared the mammary tumors developed in Gata3+/- and Brca1+/- mice under the same p18mt background." (PMID 34373738, 2021). "BRCA1 and BRCA2 are tumor suppressors frequently found mutated in breast cancers." (PMID 34445553, 2021). "This repair capacity (RECAP) test found that 19% of the unselected primary breast tumors (out of 125 breast cancer cases) showed a HRD phenotype, which could be explained by BRCA1/2 mutations or BRCA1 promoter hypermethylation in most cases." (PMID 33670893, 2021). "In contrast, a literature-based study revealed that breast cancer in young women (≤40 years) was differentially enriched with gene sets representing luminal progenitor cells, immature mammary stem cells, and high levels of RANKL, c-kit, and BRCA1 mutations." (PMID 33807872, 2021). "A subsequent prospective study by the same authors found no impact on the reduction of breast cancer risk associated with RRBSO in BRCA1/2 mutation carriers." (PMID 33885953, 2021).
breast cancer (continued). "The breast cancer cell lines were stimulated with CM of a large panel of ADSCs and the BRCA1-mutated cell lines revealed no higher proliferation compared to the matching wild-type breast cancer cells." (PMID 34228231, 2021). "BRCA2 (breast cancer susceptibility gene 2) was identified in 1995 by Wooster and colleagues, by analyzing BRCA1 mutation-negative breast cancer families, including male patients with breast cancer." (PMID 32862296, 2021). "Similarly, germline variants localized in consensus regions for “RNA binding protein” and miRNA located in 3′UTR of BRCA1 and PTEN have been associated with breast cancer risk." (PMID 34299313, 2021). "The stimulation of breast cancer cells with estrogen disrupts the endogenous complex of BRCA1-ER-α." (PMID 35008272, 2021). "High MD combined with BRCA1/2 gene mutations synergistically increases breast cancer risk, yet BRCA1/2 mutations alone or in combination do not increase MD or exacerbate the inherent tissue stiffness that high MD creates." (PMID 34209669, 2021). "The co-injection of BRCA1+/− iMSCs and 4T1 breast cancer cells into mouse mammary fat pads gave rise to highly aggressive tumor growth (2-fold increase in tumor volume compared to 4T1 alone, p = 0.01283) and a higher prevalence of spontaneous metastatic spread to the lungs." (PMID 33513753, 2021). "We previously reported the profile of BRCA1/2 mutations in a cohort of 103 Egyptian female breast cancer patients who were not selected on the basis of age at onset of breast cancer or family history." (PMID 34206661, 2021). "Recurrent BRCA1 and BRCA2 mutations in breast cancer patients of African ancestry." (PMID 35096615, 2021). "The NF1 gene is located on the long arm of chromosome 17, which also contains the BRCA1 gene, and some have suggested possible concomitance of NF1 and hereditary breast cancer, though few cases of breast cancer in patients with both NF1 and BRCA1 mutations have actually been reported." (PMID 33842116, 2021). "Talazoparib was first FDA-approved in October 2018 for advanced BRCA1/2-mutant breast cancer." (PMID 34945003, 2021). "This study identified putative pathogenic variants in ATM, BRCA1, BRCA2, CHEK2, and PALB2 as the most prominent genes for breast cancer, harboring protein-truncating variants that confer significant disease risks (odds ratio of 2.10 to 10.57) to overall breast cancer risk." (PMID 34439109, 2021). "Notably, the breast cancer genes BRCA1 and BRCA2, two important HR players, are the most frequently mutated genes in familial breast and ovarian cancer." (PMID 33923105, 2021). "Here, we compare the breast cancer cell line HCC1937, carrying a protein-truncation mutation in one allele of BRCA1 while the other allele is lost, complemented with an empty plasmid (BRCA1null), with its isogenic counterpart expressing a wild-type BRCA1 cDNA (BRCA1wt)." (PMID 34599155, 2021). "In breast cancer, BRCA1 gene may induce STC1 to express; STC1 and STC2 in tumor tissues indicate over expression in ER+ breast cancer cells, hormones is an essential element to regulate the expression of STC2." (PMID 37287492, 2021). "The complex origin of most breast cancers may thus be a combination of the genetic propensity (i.e., BRCA1/2 status) in conjunction with the local hormonal milieu that may be subsequently impacted by environmental factors, such as diet and/or obesity." (PMID 34884317, 2021). "This mouse model offered a notably large amount of information that greatly facilitated our understanding of the gender- and tissue-specific tumor suppressor functions of BRCA1 and enriched insights into applying these preclinical models of disease to breast cancer research." (PMID 33842308, 2021). "The role of BRCA1/2 in survival among breast cancer patients has been studied widely." (PMID 34857041, 2021).